AHR (aryl hydrocarbon receptor)
Diseases named in the same sentence as AHR in open-access papers (continued):
Sharing a sentence is not in itself a finding about the gene and the disease.
tumor (continued). "The results also demonstrated that AhR knockout in human BC cells could increase chemotherapeutic-induced apoptosis and reduce mice tumor growth." (PMID 36831661, 2023). "However, it has been reported that 3-methylcholanthrene activates the EGFR/ERK/c-Fos signaling in CAFs through an aryl hydrocarbon receptor (AhR)-GPER mechanism favoring the tumor growth via the up-regulation of cyclin D1 and CYP1B1." (PMID 37834441, 2023). "Analysis of the gene ontogenies of AHR-associated modules containing IL4I1 in tumors suggests that the IL4I1-AHR axis may promote tumor growth and metastasis through tumor cell-intrinsic and paracrine mechanisms." (PMID 37394584, 2023). "However, AHR activation can have both pro- and anti-tumourigenic actions depending upon the cell line or tumour model used." (PMID 36725335, 2023). "The key evidence of tumor suppressor-like activity of AHR was provided by AHR gene knockout model of mouse that showed increased liver tumorigenesis induced by diethylnitrosamine (DEN) in the AHR knockout mice." (PMID 37151890, 2023). "To test whether the effect of AhR was dependent on its transcriptional function, we treated tumor cells with actinomycin D, an mRNA synthesis inhibitor, and found that the effect of Kyn on STING expression was not influenced by inhibition of mRNA synthesis." (PMID 37670034, 2023). "Selective inhibition of AHR combined with PD-1 therapy can effectively delay tumor growth." (PMID 37936703, 2023). "The purpose of this article was to summarize and discuss the tumor-suppressive functions of AhR." (PMID 37106727, 2023). "Moreover, AhR signaling upregulates immune-regulatory factors and can generate a pro-tumorigenic microenvironment enabling tumor promotion as discussed in this review." (PMID 37696458, 2023). "There is a wide spectrum of non-carcinogenic AHR agonists, such as those naturally originated flavonoids, indole derivatives, tryptophan metabolites, etc., that may be applied for boosting the tumor suppressor-like activity of AHR." (PMID 37151890, 2023). "Moreover, inoculating AHR(C300A)- or AHR(C300)-overexpressing DRCs into NSG mice, we found that C300A mutation inhibited tumor growth." (PMID 38099490, 2023). "AhR can act as a tumor suppressor via tumor suppressor miRNA regulation." (PMID 36831661, 2023). "In the TCGA-KIRC tumour samples, increasing VHL copy number loss was associated with a significant increase in the HIF composite score (P = 7 × 10−6), whereas an inverse association was seen for the AHR composite score (P = 5 × 10−11)." (PMID 36725335, 2023). "For instance, the AhR may directly regulate inflammatory responses and immune cells in the tumor microenvironment." (PMID 37696458, 2023). "In addition, inoculating Tet-inducible AHR shRNA DRCs into NSG mice also resulted in the inhibition of tumor growth." (PMID 38099490, 2023). "In particular, AhR can regulate angiogenesis during tumor progression." (PMID 37305351, 2023). "UCHL3 promoted tumor stem-like properties through stabilization of AhR." (PMID 37830596, 2023). "The increased NO production observed in the PBMCs of the Low AHR group suggests that NO may contribute to the immunosuppressive tumour microenvironment in PDAC." (PMID 37760608, 2023). "Additionally, TET3 and AHR expression levels were lower in the tumor grade 1 subgroup compared to the tumor grade 2/3 subgroups and lower in the tumor grade 2 subgroup compared to the tumor grade 3 subgroup (P < 0.001)." (PMID 37718440, 2023). "In contrast, the tumor-promoting properties of certain AhR agonists have been reported." (PMID 37241719, 2023).
tumor (continued). "Importantly, AhR and interconnected proteome of the tumor microenvironment can drive malignant transformation, drug resistance, epithelial-to-mesenchymal transition, immune evasion and metastatic spread of cancer cells to secondary sites." (PMID 37830596, 2023). "Taken together, the overexpression of TET3 and AHR in THCA indicates their involvement in promoting tumor aggressiveness and targeting them could potentially serve as a treatment strategy for THCA." (PMID 37718440, 2023). "A recent study revealed that in contrast to dioxin-like chemicals, the treatment of human epithelial cells with PAHs including B[a]P results in an auto-/paracrine activation of EGFR, which can be an important contributing factor in AhR-mediated tumor promotion." (PMID 37696458, 2023). "Also for several tumor suppressors AHR-mediated promoter hypermethylation has been described as a mechanism for transcriptional repression." (PMID 37696456, 2023). "Activation of AHR contributes to tumor initiation through genotoxicity." (PMID 37179416, 2023). "Sustained activation of AHR encourages tumor growth and affects immune defense." (PMID 37179416, 2023). "However, AhR knockdown has also been shown to impair angiogenesis and compromise tumor xenograft growth in mice, by a mechanism involving AhR-dependent VEGF activation in endothelial cells." (PMID 37696458, 2023). "In addition, tumor-repopulating cells (TRCs) are reported to promote programmed cell death-1 (PD-1) expression on CD8+T cells via transcellular kynurenine (Kyn)-aryl hydrocarbon receptor (AhR) signaling." (PMID 37007125, 2023). "The KYN can activate AHR, which inhibit the anti-tumor immunity." (PMID 36925967, 2023). "Moreover, kynurenine from tumor-repopulating T-cells (TRCs) have been reported to drive AhR dependent upregulation of programmed cell death protein 1 (PD-1) in CD8+ T cells, with potential consequences for cancer immunotherapies." (PMID 37696458, 2023). "AHR possesses tumor suppressor-like property in human cancers." (PMID 37151890, 2023). "AhR helps maintain a stem cell-like expression signature in tumor cells." (PMID 37781044, 2023). "Inhibition of Jdp2 expression significantly increased the growth of tumors but could be rescued by AhR overexpression, which suggested that Jdp2 acts as a tumor suppressor upstream of the AhR-Nrf2 gene battery." (PMID 37596694, 2023). "Consequently, AHR has been described as a tumor suppressor or an oncogene, depending on the types of cancer and study cohorts in the same type of cancer." (PMID 35465323, 2022). "In addition, AHR inhibits the function of CD8+ T cells by regulating the function of tumor-associated macrophages, resulting in anti-tumor immune responses." (PMID 36407768, 2022). "Targeting AhR must be dependent on tumor-specific AhR expression." (PMID 36258210, 2022). "Cancer cell-derived kynurenine activation of the AhR, driving a decrease in melatonin will increase tolerogenic Tregs, whilst the loss of melatonin optimization of DC function contributes to suppressed activation of CD8+ t cells in the tumor microenvironment." (PMID 36613754, 2022). "The complexity of AhR, with evidence for both oncogenic and tumor suppressor roles is discussed." (PMID 36588678, 2022). "This review also highlights the role of AhR at the interface between historical and existing systemic practices - which reinforce residential segregation and environmental injustice - and the molecular drivers of aggressive tumor biology." (PMID 36588678, 2022). "AhR and its interacting ligands are involved in tumor immunotherapy." (PMID 35892593, 2022). "A co-culture of F. nucleatum and CRC cells could increase formate secretion and cancer glutamine metabolism, which drove CRC tumor invasion and proliferation by triggering aryl hydrocarbon receptor (AhR) signaling." (PMID 35877336, 2022).
tumor (continued). "Using mRNA from diffuse and intestinal GC tumor samples of a Western cohort, this study reports the expression level of the immunomodulatory aryl-hydrocarbon receptor (AhR), and genes involved in immune suppression (PD1, PD-L1, PD-L2) and the early steps of tryptophan metabolism (IDO1, IDO2, TDO2)." (PMID 35203450, 2022). "Current studies provided evidence that Kyn could mediate the activation of AhR signals, resulting in tumor development in several tumor types." (PMID 35831824, 2022). "Moreover, the amino acid tryptophan is catabolized by tryptophan-2,3-dioxygenase and indoleamine 2,3 dioxygenase (IDO) in human tumor cells into kynurenine, an endogenous ligand of the transcription factor aryl hydrocarbon receptor (AHR)." (PMID 36269001, 2022). "Furthermore, overexpression of NUPR1 in tumor cells significantly increased the distribution of AhR to lysosome marker LAMP1." (PMID 36258210, 2022). "The overall impact of the AhR on cell proliferation and cell cycle progression is likely to be tissue specific, and it can be affected by factors involved in cell transformation, as well as by the tumor microenvironment." (PMID 36077780, 2022). "AhR is often overexpressed in tumor cells of various tissue origin, and several studies have indicated that AhR may also contribute to regulation of cellular metabolism, including synthesis of fatty acids (FA), one of the major steps in metabolic transition." (PMID 36077780, 2022). "Furthermore, LEF can act as aryl hydrocarbon receptor (AhR) agonist by stimulating AhR which can inhibit cancer cells’ proliferation and act as a tumor suppressor in cancer animal models." (PMID 35616281, 2022). "In addition, the activation of AhR by FICZ in NK cells impeded the growth of tumor cells in a wild-type immunocompetent mice model of lymphoma and T-cell deficient mice model of melanoma." (PMID 35173722, 2022). "Beneficial AhR ligands: The aryl hydrocarbon receptor (AhR), a ligand-dependent transcription factor with diverse functions in inflammation, detoxification, and homeostasis, has been identified as a tumor suppressor in mouse CRC models." (PMID 35967333, 2022). "Nuclear AhR localization results in a higher tumor grade, more poorly differentiated cells, and poor prognosis, suggesting that AhR may contribute to increasing cancer aggression." (PMID 35678668, 2022). "As to whether the priming effect of tumor-derived kynurenine on AhR activation in platelets contributes to variations in the platelet NAS/melatonin ratio, in turn driving an increase in TrkB-T levels, activation and ligands, will be important to determine." (PMID 36613754, 2022). "In addition to the response to the cytotoxicity of 2,3,7,8-tetrachlorodibenzo-p-dioxin (TCDD) and other extracellular pollutants, AhR also serves as an indispensable regulator in immune responses and tumor progression." (PMID 35831824, 2022). "AhR plays a critical role in carcinogenesis and tumor immunity." (PMID 36588678, 2022). "TDO2 increases glycolysis through activation of the Kyn-AhR pathway to promote tumour cell growth." (PMID 36147503, 2022). "Furthermore, Trp and its metabolites stimulate AHR activity and induce tumor cell proliferation and tumor escape in colorectal cancer." (PMID 35451695, 2022). "Low cytosolic AhR levels and positive aromatase were associated with more aggressive ER negative (ER-) tumors; however, AhR tumor genotypes did not correlate with AhR protein levels." (PMID 36428667, 2022). "Pluripotency and reprogramming inducers OCT4 and NANOG, both repressed in an AhR-dependent manner during liver tumorigenesis and regeneration, were overexpressed in AhR-null livers in parallel with their enhanced senescence and tumor burden." (PMID 35619220, 2022). "Some critical questions remain, including how AhR activation modulates the tumor microenvironment." (PMID 36588678, 2022).
tumor (continued). "Indeed, the AhR inhibitor DMF exhibited efficient tumor-suppressive effects in this mice model and prolonged the overall survival of tumor-bearing mice." (PMID 35831824, 2022). "We established a mouse xenograft model of NSCLC, wherein the injection of LINC00665 overexpressing PC9 cells was found to promote the tumor weight in mice under irradiation, and such promoting effects could be reversed by AhR knockdown." (PMID 35918714, 2022). "Although experimental evidence is yet lacking, it is conceivable that at least in advanced stages of cutaneous SCC, the AHR may play a comparable role in modulating tumor immunity." (PMID 35311158, 2022). "Finally, inhibition of AhR signals efficiently prevented tumor growth and development of EGFR TKIs resistance, eventually improved the outcome of EGFR TKIs, and described a promising therapeutic strategy for NSCLC." (PMID 35831824, 2022). "Resveratrol, a clinically compatible AhR antagonist that eliminates its prolonged harmful activation, in combination with BRAFi, has been shown to reduce the number of BRAFi-resistant cells and delay tumor growth." (PMID 35458697, 2022). "Different reports suggested a tumor suppressor role for AhR." (PMID 35321750, 2022). "We wondered whether STS could weaken the effect of tumor cells on Treg production through the IDO-kynurenine-AhR axis in vitro." (PMID 35571116, 2022). "On the one hand, the Trp–Kyn–AHR pathway promotes Treg cell differentiation and also upregulates PD-1 expression levels, inhibits T cell activity, and promotes immune tolerance; on the other hand, AHR is a tumor-suppressor gene in GBM, and the deletion of AHR enhances GBM tumor growth and invasion." (PMID 36497459, 2022). "Besides this role in tissue homeostasis, one enthralling feature of AHR is its capacity of acting as an oncogene or tumor suppressor depending on the specific organ, tissue and cell type." (PMID 35465323, 2022). "Kyn enters cells and activates AhR, resulting in tumor proliferation and immune suppression." (PMID 35972800, 2022). "In addition, the expression of IDO1 in the tumor microenvironnement of ovarian cancer promoted PD-1 expression in T cells via AhR activation." (PMID 35173722, 2022). "Thus, more AhR-relevant studies involving the tumor microenvironment, immune cells, immune modulators, and the immunotherapeutic response are warranted." (PMID 34290693, 2021). "Strategies to concomitantly target the IDO1 and AHR pathways may overcome immune suppression and enhance anti-tumor immunity in EOC and other solid tumors." (PMID 34025677, 2021). "Furthermore, Kyn and Kyna are both ligands of aryl hydrocarbon receptor (AhR), which is involved in multiple physiological functions, tumor invasion and/or migration." (PMID 34770460, 2021). "The AHR-related pathway is another pathway that was inhibited in the tumor xenograft." (PMID 33808801, 2021). "Although not all the cancers exhibited an association between their tumor immune microenvironment and AhR, these findings highlight the immunological effect of AhR in specific cancers, which will serve as an effective means for targeting them." (PMID 34290693, 2021). "It has been shown that AML blasts may induce AhR expression in NK cell precursors, impairing their maturation and functions, and thus favoring tumor escape from NK cell-mediated control." (PMID 33467134, 2021). "Notwithstanding emerging evidence that AHRR may serve a protective role against TCDD-induced pathologies such as tumor growth and inflammation, very little is still known about its function in regulating AHR in different contexts." (PMID 34001975, 2021). "Constitutively high AhR expression and nuclear localization is observed in invasive tumor tissues and malignant tumor cell lines, which may suggest its involvement in the inflammatory response and cell cycle progression." (PMID 34290693, 2021).
tumor (continued). "The inhibition of AHR could lead to decreased disposal of toxic compounds, including reactive oxygen species generated within cell or from tumor microenvironment." (PMID 33808801, 2021). "Overall, these studies underscore the role of AhR as a tumor suppressor." (PMID 33451095, 2021). "Moreover, in particular macrophages and T cells, but also oligodendrocytes and most of the malignant tumor cell sub-populations showed AHR activation." (PMID 34646367, 2021). "Although AhR was not closely associated with age (5/33), gender (3/33), or tumor stage (3/21) in any of the studied human cancers, it exhibited potential prognostic value for predicting patient survival." (PMID 34290693, 2021). "While the exact AHR ligand has yet to be identified, activation of AHR may yield an overall tumor-suppressive environment." (PMID 33477248, 2021). "The role of AhR in cancer development is complex (oncogene or tumor suppressor)." (PMID 33451095, 2021). "However, blockade of AhR directly suppressed the IL-6 secretion and tumor development induced by TDO2." (PMID 34657635, 2021). "It was suspected that AhR is a pro-tumor agent, although evidence suggests that, depending on cancer type it may have an opposite, tumor-suppressive role." (PMID 34071442, 2021). "Moreover, kynurenine is an endogenous ligand that promotes tumor proliferation; it can bind to and activate aryl hydrocarbon receptor (AHR) to exert biological effects, both of which contribute to the occurrence and development of tumors." (PMID 34830310, 2021). "Importantly, the AhR correlation signatures identified in cell lines (GDSC database) were also observed in patient tumor samples (TCGA)." (PMID 33451095, 2021). "Importantly, AHR activation by this pathway has been shown to contribute to immune escape mechanisms leading to an immunosuppressive tumor microenvironment (TME)." (PMID 34572746, 2021). "The expression of AhR was predominately distributed in the nucleus of tumor cells in LSCC." (PMID 34941188, 2021). "Also, AhR participates in liver development, regulates liver regeneration, and inhibits tumor development." (PMID 33777316, 2021). "Furthermore, L-Kyn promotes tumor growth by inhibiting anti-tumor immune responses via AhR in an autocrine/paracrine fashion." (PMID 34867973, 2021). "This difference between tumour subpopulations might be explained by their distinct expression profiles that TRCs exhibit higher levels of IDO1 and AhR than differentiated tumour cells do." (PMID 34539663, 2021). "Intratumoral aromatase was associated with several aggressive tumor characteristics but not with AhR levels or prognosis." (PMID 34094928, 2021). "In addition, AHR can participate in the regulation of the activities of astrocytes and microglia, which play a substantial role in the immune activities of the tumor microenvironment." (PMID 34659216, 2021). "However, higher doses of I3C increased colonic lesions and tumor initiation due to overactivation of AhR in a murine model of hepatocarcinogenesis." (PMID 33916690, 2021). "Many investigators speculate AhR is a double-edged sword that can either act as a tumor suppressor or promoter." (PMID 34249001, 2021). "Their carcinogenic and mutagenic effects require metabolic activation primarily by cytochrome P450 1 family enzymes (CYPs); the expression of these enzymes can be modulated by aryl hydrocarbon receptor (AhR) activation and the tumour microenvironment, involving mediators of inflammation." (PMID 33961948, 2021). "Inhibitory pathways related to AHR and its metabolites may be activated in the tumor microenvironment, thus promoting immune escape and tumor progression." (PMID 34784845, 2021). "Moreover, the activation of AHR hampers the performance of dendritic cells and T cells, which play a role in anti-tumor." (PMID 34804978, 2021).